ERMARD (ER membrane associated RNA degradation)
Description:
May play a role in neuronal migration during embryonic development.
Synonyms: C6orf70; FLJ11152; dJ266L20.3; PVNH6
Tractability: Antibody: UniProt predicts a signal peptide or a membrane-spanning region. PROTAC: ubiquitination databases record sites on it.
Gene: Protein-coding gene on chromosome 6 (169,751,567 to 169,781,600, forward strand). Ensembl gene ENSG00000130023.
Subcellular location: Endoplasmic reticulum membrane
Subcellular location (Human Protein Atlas): Cytosol
Gene Ontology:
Cellular component: endoplasmic reticulum membrane
Genetic constraint (gnomAD): Loss-of-function variants: 59 observed, 73.61 expected, observed/expected ratio (o/e) 0.8, 90% interval 0.65 to 1. The upper end of that interval is the gene's LOEUF score, 1, which puts it in group 4 of 6, group 1 being the genes least tolerant of losing a copy. Missense variants: 788 observed, 791.65 expected, observed/expected ratio (o/e) 1, 90% interval 0.94 to 1.06. Synonymous variants: 262 observed, 291.77 expected, observed/expected ratio (o/e) 0.9, 90% interval 0.81 to 1.
Gene-disease validity (ClinGen):
ClinGen rates the evidence that ERMARD causes each of these diseases.
periventricular nodular heterotopia (autosomal dominant): Limited. Periventricular nodular heterotopia (PNH) is a brain malformation, due to abnormal neuronal migration, in which a subset of neurons fails to migrate into the developing cerebral cortex and remains as nodules that line the ventricular surface.
Homologues: Orthologues: chimpanzee ERMARD (98% identical), macaque ERMARD (94% identical), dog ERMARD (75% identical), rabbit ERMARD (73% identical), guinea pig ERMARD (71% identical), rat Ermard (71% identical), pig ERMARD (69% identical), mouse Ermard (64% identical), tropical clawed frog ermard (47% identical), mouse Ermardl1 (45% identical), mouse Ermardl2 (45% identical).
Diseases named in the same sentence as ERMARD in open-access papers:
ERMARD is named in the same sentence as 9 diseases in open-access papers, as found by Europe PMC text mining. Sharing a sentence is not in itself a finding about the gene and the disease. The quoted sentences say what the papers report.
periventricular nodular heterotopia (3 papers, 2016 to 2021). "Furthermore, it was reported that heterozygous variants in ERMARD (C6orf70) are associated with brain anomalies and syndromic dominant forms of periventricular nodular heterotopia in humans." (PMID 34573664, 2021). "In addition, no variants were observed in the known or possible genes for periventricular heterotopia including FLNA, ARFGEF2 and ERMARD, nor were pathogenic variants seen in other known genes implicated for brain malformation syndromes, intellectual disability or ADHD conditions." (PMID 28868155, 2016).
Dandy-Walker malformation (1 paper, 2016). "Furthermore, our data suggests the involvement of CNTN6 and KLHL15 in the etiology of agenesis of the corpus callosum, the involvement of RASD1 and PTPRD in Dandy-Walker malformation, and the involvement of ERMARD in ventriculomegaly." (PMID 27087860, 2016).
periventricular nodular heterotopia 6 (1 paper, 2016). "Moreover, heterozygous ERMARD mutations have been associated with brain anomalies and periventricular nodular heterotopia 6 (OMIM #615544)." (PMID 27087860, 2016).
subependymal nodular heterotopia (1 paper, 2022). "Subependymal nodular heterotopias have been described in patients with chromosomal rearrangements, as well as associated with intragenic gene mutations (e.g., in FLNA, ARFGEF2, DCHS1, FAT4, ERMARD, and NEDD4L)." (PMID 35585091, 2022).
tumor (1 paper, 2020). "Interestingly, parallel evolutionary patterns were exhibited in the phylogenetic trees, including mutations in MLLT10, WDR5, and ERMARD, which indicated the diversity of tumor genome evolution." (PMID 33078899, 2020).
ERMARD also shares sentences with these, for which no sentence is quoted: Hydrocephalus (1 paper); Intellectual disability (1); Periventricular heterotopia (1); Ventriculomegaly (1).